HTR1B (5-hydroxytryptamine receptor 1B)
Diseases named in the same sentence as HTR1B in open-access papers (continued):
Sharing a sentence is not in itself a finding about the gene and the disease.
tumor (12 papers, 2009 to 2026). "HTR1B and 2A were not expressed in either pHMEC or established breast cell lines, which implies that expression in tumor specimens represents the presence of stromal or vascular elements, which typically express HTR1B and 2A in smooth muscle cells." (PMID 19903352, 2009). "Collectively, the inhibition of expression of growth factors such as PRL, PDGF, HTR1B, and VEGF in fibroid xenografts provides another mechanism for reducing tumor cell proliferation and angiogenesis in fibroids." (PMID 38994944, 2024).
cancer (10 papers, 2009 to 2025). A tumor composed of atypical neoplastic, often pleomorphic cells that invade other tissues. "Diploid and shallow deletion were the primary alterations in pan-cancer, which were associated with the overexpression of HTR1B/1D/1F/2A/7." (PMID 39766808, 2024). "Mechanistically, isovaleric acid upregulates Tph2 in intestinal serotonergic neurons, increasing 5-HT production, which activates the HTR1B/1D/1F-Wnt/β-catenin pathway in cancer stem cells (CSCs) to promote self-renewal and tumorigenesis." (PMID 40510674, 2025). "In pan-cancer, high expression of HTR1B/1F/2B/4/7 was positively correlated with the expression of PD-1, PD-L1, and CTLA4 while the expression of HTR1A was negatively correlated with the expression of PD-1, PD-L1, and CTLA4 in GLB, LGG, SARC, OV, and PAAD." (PMID 39766808, 2024). "Among all of the receptor isoforms, HTR1B, 1D, 1F, 2A, 2B, 2C, 3, 4, 5A, 7 were found to be expressed in breast tissues (cancer and other)." (PMID 19903352, 2009). "It remains to be studied whether in AML and MDS and other cancers with HTR1B over‐expression thrombosis is more frequent as well as whether the same cells over‐express it like in MPNs." (PMID 39183370, 2024). "The expression level of HTGPCRs in different tumors showed the specificity of genes and tumors, for example, HTR1B and HTR2B were lowly expressed in most cancers while HTR1D and HTR7 were highly expressed in most cancers." (PMID 39766808, 2024). "In addition to the C3, for these genes (CXCL8, CX3CR1, GRM8, HTR1B, HTR1D, PTGER3, SSTR1 and SUCNR1) were related to survival in the ACC and it was also could be useful in other cancers 24-31." (PMID 34220331, 2021).
psychiatric disorder (4 papers, 2018 to 2024). A disorder characterized by behavioral and/or psychological abnormalities, often accompanied by physical symptoms. "The 5-HT 1B receptor (5-HT1B) is encoded by HTR1B and is closely associated with a variety of mental illnesses." (PMID 33036580, 2020). "The serotonin receptor 1B (HTR1B) gene has been proposed to play putative roles in the development of multiple emotional and psychiatric disorders." (PMID 30231895, 2018).
HTR1B also shares sentences with these, for which no sentence is quoted: Cerebral ischemia (3 papers); Cognitive impairment (3); Dyskinesia (3); ischemia (3); pancreatic cancer (3); substance abuse (3); asthma (2); cardiac diseases (2); ischemic stroke (2); leukemia (2); obsessive-compulsive disorder (2); psychosis (2); Stroke (2); substance dependence (2); Alzheimer disease (1); anxiety disorder (1); bacterial infection (1); cardiac ischemia (1); cerebral artery (1); cerebrovascular diseases (1); chronic obstructive pulmonary disease (1); Cluster headache (1); cocaine abuse (1); cocaine dependence (1); coronary artery vasospasm (1); cortical atrophy (1); developmental delay (1); Ebola (1); endocrine diseases (1); endometrial cancer (1).
A further 29 diseases each share a sentence with HTR1B in 1 paper.